G3BP2 (G3BP stress granule assembly factor 2)
Diseases named in the same sentence as G3BP2 in open-access papers (continued):
Sharing a sentence is not in itself a finding about the gene and the disease.
tumor (continued). "In this study, we confirmed that G3BP2 protein is up-regulated in human NSCLC tumor tissues." (PMID 34521423, 2021). "The results demonstrated that EEF2, G3BP1, G3BP2, PRPF8, RECQL4, STOML2, and UBB exhibited significantly higher expression levels in the majority of tumor tissues, whereas METTL3 and NR2C2 showed a widespread downregulation trend." (PMID 41341921, 2025). "Augmented dipeptides induce the expression of MAP4K4 and promote the phosphorylation of G3BP2 at Thr227, leading to the activation of epithelial‐mesenchymal transition (EMT) signaling, which facilitates the metastasis of tumor cells." (PMID 38639383, 2024). "Mechanistically, activated MAP4K4 phosphorylates G3BP2 at T227, thereby promoting EMT signaling and subsequent tumor cell metastasis." (PMID 38639383, 2024). "Compared with normal cell, SG-related components are upregulated in various tumor cell, including G3BP1 and G3BP2." (PMID 37179344, 2023). "By the way, ECM stiffness transduces mechanical signal to TWIST1, then destroys the interaction between TWIST1 and Ras-GTPase activating protein SH3 domain-binding protein 2 (G3BP2), which induces nuclear import of TWIST1 and EMT in tumor." (PMID 36906534, 2023). "High matrix stiffness leads to the release of Twist1 from GAP SH3 domain-binding protein 2 (G3BP2), thereby promoting Twist1 nuclear translocation and enhancing EMT in tumor cells." (PMID 35331296, 2022). "Furthermore, we also demonstrated that overexpression of circFNDC3B could effectively inhibit cell proliferation and invasion in vitro and suppress tumor growth and lymphatic metastasis in vivo by targeting the miR-1178-3p/G3BP2/SRC/FAK axis, suggesting a key role for circFNDC3B in BC progression." (PMID 30458784, 2018). "G3BP1/G3BP2 double-knockout (dKO) U2OS cells was further constructed, which were rescued with G3BP1-WT, G3BP1-N258A, and G3BP1-N309A to further validate that the cleavage sites at N258 and N309 of G3BP1 actually occurred in tumor cells during drug treatment." (PMID 40858563, 2025). "Notably, depletion of G3BP2 and USP7 independently retarded tumor growth, but the efficacy of USP7 silencing was rescued by G3BP2 expression." (PMID 36878903, 2023). "G3BP2, a member of the Ras-GTPase-activating protein (RasGAP) SH3 domain-binding protein (G3BP) family, is significantly overexpressed in multiple types of human tumours and contributes to tumour invasion." (PMID 33397425, 2021). "We conducted immunohistochemical (IHC) staining using antibodies against G3BP1 and G3BP2 with the paired lung sections derived from the tumor (bottom) and non-tumor regions (top)." (PMID 34521423, 2021). "G3BP2, a member of the Ras-GTPase-activating protein (RasGAP) SH3 domain-binding protein (G3BP) family, is remarkably overexpressed in various human cancers and contributes to tumor invasion." (PMID 30458784, 2018). "To determine whether the Eps8l2-G3bp2 axis contributes to tumor development in this AOM/DSS model, we examined G3bp2 and Ki67 expression by IHC staining and found a significant decrease of G3bp2 and Ki67 expression levels in tumor tissues from Eps8l2−/− mice." (PMID 40783393, 2025). "Interestingly, we found that the ratio of MG53/G3BP2 is significantly reduced in tumor compared to non-tumor samples (n=20)." (PMID 34521423, 2021).
cancer (26 papers, 2011 to 2026). A tumor composed of atypical neoplastic, often pleomorphic cells that invade other tissues. "Future studies will be required to dissect the potential role of MG53 in modulating the G3BP2/G3BP1 complex formation associated with SG signaling in cancer cells." (PMID 34521423, 2021). "Hyperactivation of G3BP2 is associated with various pathological conditions, especially cancers." (PMID 36878903, 2023). "To understand the impact of G3BP1 or G3BP2 on the RG7388-induced NOXA/Caspase-3 axis-mediated cancer cell death, we utilized siRNA technology to knock down G3BP1 and G3BP2, respectively." (PMID 40523886, 2025). "This suggests the difference of the role of the same gene in different cancer type and large clinical samples are needed to confirm the role of G3BP2 and TM9SF2 in ccRCC." (PMID 38735008, 2024). "An increasing number of studies have revealed the molecular mechanism of G3BP2 in promoting cancer progression." (PMID 34782720, 2022). "CD36, PDK4, and THBS1 were highly expressed in cancer tissues, and G3BP2, PTPRB, and TMEM125 were lowly expressed in cancer tissues." (PMID 36147333, 2022). "As a member of the G3BP family, G3BP stress granule assembly factor 2 (G3BP2) has been reported to be highly expressed in cancer cells and exert carcinogenic influence in certain cancers by different researches." (PMID 35761386, 2022). "In summary, our work has revealed that PD‐L1 level is increased in starved or chemically stressed cancer cells and level of PD‐L1 protein in cancer cells is dependent on G3BP2." (PMID 33525064, 2021). "Total lysates prepared from cancer cells were immunoprecipitated using either a normal rabbit IgG or anti‐G3BP2 antibody, and immunoprecipitated PD‐L1 RNA was detected by qPCR with PD‐L1 primers." (PMID 33525064, 2021). "We further confirmed that G3BP2 suppression decreases PD‐L1 protein in cancer cells using immunostaining." (PMID 33525064, 2021). "In this study, we found that G3BP2, a key SG protein, plays a critical role in regulating PD‐L1 expression in stressed cancer cells." (PMID 33525064, 2021). "G3BP1 and PD-L1 were shown to be highly co-expressed in cancer tissues.G3BP2 knockdown or silencing by c108 also reduced PD-L1 expression due to enhanced mRNA degradation." (PMID 35004322, 2021). "Mapping results indicated that G3BP2 protein binds to a coding region of the PD‐L1 mRNA in stressed cancer cells." (PMID 33525064, 2021). "By identifying the SG forming protein G3BP2 as a common denominator of stemness and immunosuppression, our study provides a compelling mechanism linking these two hallmarks of cancer." (PMID 33525064, 2021). "The abundant cytosolic distribution of G3BP2 is consistent with its role in the cytosolic SG formation in human cancer patients." (PMID 34521423, 2021). "IHC staining revealed an abundant cytosolic distribution of G3BP2, which is consistent with its role in the cytosolic SG formation in human cancer patients." (PMID 34521423, 2021). "As a member of the G3BP family, G3BP2 has been to be reported remarkably overexpressed in many human cancers, including BC." (PMID 30458784, 2018). "Relatively few post-translational modifications of G3BP2 in human cancer cells have been reported." (PMID 36878903, 2023). "Regulation of G3BP2 ubiquitination and deubiquitination in cancer cells is of great interest but remains unclear." (PMID 36878903, 2023). "Inhibition of G3BP2 could decline PD-L1 expression in cancer cells, thereby facilitating anticancer immunotherapy." (PMID 37884630, 2023). "Thus, we conclude that methylation of G3BP2 R468 promotes the proliferation and migration of cancer cells in vitro." (PMID 36878903, 2023). "Among these, G3BP2 could regulate cancer stemness via upregulating the expressions of stem cell markers Oct-4 and Nanog23." (PMID 37884630, 2023). "It has been shown that G3BP2 often overexpressed in some cancers and acted as an oncogene." (PMID 37884630, 2023).
cancer (continued). "Although an increasing number of studies have demonstrated the involvement of G3BP2 in several human cancers, how G3BP2 interacts with long noncoding RNAs and regulates mRNA transcripts in mediating ESCC metastasis remains unclear." (PMID 34782720, 2022). "The G3BP2 (Ras GTPase-activating protein-binding protein 2) proteins play an essential role in the formation of the stress granules, a mechanism that is thought to protect cancer cells from apoptosis or induce resistance to radiation or anticancer drug treatments." (PMID 35954483, 2022). "This study shows that G3BP2 also upregulates PD‐L1 under stress in cancer cells, revealing a previously unknown connection between stemness programs, stress responses, and immune checkpoint control." (PMID 33525064, 2021). "Cancer cells develop resistance to chemotherapeutic intervention by excessive formation of stress granules (SGs), which are modulated by an oncogenic protein G3BP2." (PMID 34521423, 2021). "Both G3BP1 and G3BP2 are dramatically overexpressed in human cancers, especially breast cancer, suggesting that they may be related to cancer progression." (PMID 25962958, 2015). "Interestingly, G3BP1 and G3BP2 exhibit differential activity and functions in cancer." (PMID 40523886, 2025). "Thus, we focused on G3BP2 because of its role in cancer stemness in the study." (PMID 37884630, 2023). "Furthermore, RNA-seq indicated that G3BP2 conferred lipid metabolism, such as fatty acid metabolism, fatty acid elongation, biosynthesis of unsaturated fatty acids and central carbon metabolism in cancer, indicating that G3BP2 globally functions in the metabolic reprogramming of carcinomas." (PMID 36878903, 2023). "CD36, THBS1, and PDK4 were highly expressed in cancer tissues, whereas PTPRB, G3BP2, and TMEM125 were lowly expressed in cancer tissues." (PMID 36147333, 2022). "G3BP2 suppression inhibited the stress‐induced expression of PD‐L1 in MCa‐PSTC, CT2A, and 4T1 cancer cells." (PMID 33525064, 2021). "G3BP2 has been reported to promote the phosphorylation of SRC and FAK, which play a vital role in cancer invasion and metastasis." (PMID 30458784, 2018). "G3BP2 and PTPRB are lowly expressed in cancer and are reliable markers for prognosis of patients." (PMID 36147333, 2022). "In addition, G3BP2, WTAP, PCIF1, HNRNPA2B1, EIF3A, and IGF2BP2 were modulated in ≥three cancer types in uncertain manners." (PMID 35211628, 2022). "We developed a unique model with the inducible secretion of MG53 in cancer cells and demonstrated that tailored overexpression of MG53 could impact G3BP2/SG signaling and mitigate NSCLC growth in a xenograft model." (PMID 34521423, 2021). "However, we noticed that all SGs nucleators (TIA-1, TIAR, G3BP1, G3BP2, and CAPRIN-1) have an “enhancing” effect on cancer development properties, whereas USP10, a SGs inhibitor, has anti-cancer properties." (PMID 32882814, 2020). "Interestingly, Snail, CD44, G3BP2, and YAP1 are targets of Wnt5A, a gene involved in invasion and metastasis of many cancers, that is regulated by NF-κB signaling pathway." (PMID 25738332, 2015). "Despite considerable analysis arranged in this study on the USP7 and G3BP2 regulatory circuit, it is not yet fully clear how USP7-G3BP2 promoted lipid metabolic reprogram cells to help the cancer state." (PMID 36878903, 2023). "Additionally, the enhanced proliferation induced by overexpression of G3BP2-WT was blocked when the absence of PRMT5, suggesting that the methylation of G3BP2 is involved in the event of PRMT5 promotes carcinoma cell growth." (PMID 36878903, 2023). "Here, we found that G3BP2 was protected by LINC01554 from ubiquitin-mediated protein degradation and stabilized HDGF mRNA transcripts to drive ESCC metastasis, which has not yet been reported during cancer progression." (PMID 34782720, 2022).
infection (17 papers, 2014 to 2026). The state of being infected such as from the introduction of a foreign agent such as serum, vaccine, antigenic substance or organism. "We performed IF analysis to assess SG formation during CVB3–2Amut infection, staining for the conventional stress granule markers G3BP2 and eIF3, as well as TIA-1 and Sam68." (PMID 40875754, 2025). "Certain genes were down-regulated in the single G3BP1 or G3BP2 KO, which indicate SG-independent roles for these proteins during infection." (PMID 37983241, 2023). "G3BP2 is also known as a stress granule assembly factor in the cytoplasm for viral replication complexes during infection of some RNA viruses." (PMID 36560452, 2022). "Like G3BP1, G3BP2 is important for SG formation and is sequestered by chikungunya virus nsP3 to disassemble SGs late in infection." (PMID 27147742, 2016). "However, protein level of G3BP2 in Vero cells was significantly reduced at 72 h in the mock infection." (PMID 36081788, 2022). "siRNA-mediated knockdown of G3BP2 was transfected into SH-SY5Y cells, followed by infection with CVB5." (PMID 40626722, 2025). "In contrast, during MNV infection, only 5 out of 21 of the cross-core stress granules proteins displayed a high enrichment with G3BP1, namely ZC3HAV1, FXR1 and G3BP2." (PMID 31905230, 2020). "Taken together, these data indicate that G3BP1, G3BP2 and CAPRIN1 interact with DENV-2 gRNA and sfRNA during infection." (PMID 24992036, 2014). "Since G3BP1, G3BP2 and CAPRIN1 had previously been determined to be critical regulators of stress granules (SG) assembly, another aspect of the cellular response to infection, we examined SG formation in infected cells and upon IFN treatment." (PMID 24992036, 2014). "In order to investigate a link between IFN-mediated antiviral activity and that of G3BP1, G3BP2 and CAPRIN1, cells depleted of these three proteins were pretreated with IFN-β before infection with DENV-2 NGC." (PMID 24992036, 2014). "Interestingly, the SL-I of ZIKV can interact with proteins related to stress granules, such as Caprin-1, G3BP1, G3BP2 and USP10, to assess the success of infection." (PMID 36982407, 2023). "After demonstrating that knocking out G3BP2 was also insufficient to inhibit SG formation, we developed a G3BP1 and G3BP2 dKO cell line, which successfully stopped SG from forming during RSV cbVG-high infection." (PMID 37983241, 2023). "Interestingly, on the seventh day after infection, the TRIM25 protein in nasopharyngeal tissue decreased significantly, with only G3BP2 and N colocalizing." (PMID 36560452, 2022). "However, in the later stage of infection, the expression of TRIM25 decreased to below the normal level, which was different from that of G3BP2." (PMID 36560452, 2022). "To further test this hypothesis and determine the importance of this mechanism during infection and for viral evasion of the IFN response, we constructed mutant DENV-2 replicons unable to sequester G3BP1, G3BP2 and CAPRIN1." (PMID 24992036, 2014). "Furthermore, G3BP2 is not cleaved by 3Cpro during infection, as the 3Cpro cleavage recognition site with a scissile glutamate-glycine bond at residue Q326 is not conserved in G3BP2." (PMID 27043612, 2016). "The N protein of SARS-CoV-2 promoting TRIM25 interacts with G3BP2 (GTPase-activating protein SH3 domain–binding protein 2), inhibiting type I interferon production in the process of infection without involving the ubiquitination of TRIM25." (PMID 40723303, 2025). "While not tested in the context of infection, this model is consistent with studies demonstrating interactions between N and M, G3BP1 and G3BP2 within stress granules, and phosphorylated N and nsp3 to promote the synthesis of viral RNA." (PMID 35728038, 2022).
neurodegenerative disease (1 paper, 2019). A disorder of the central nervous system characterized by gradual and progressive loss of neural tissue and neurologic function. "Further analyses will be required in order to elucidate how G3BP1 and G3BP2 regulate protein aggregation in neurodegenerative diseases, including PD." (PMID 31501480, 2019).
G3BP2 also shares sentences with these, for which no sentence is quoted: esophageal squamous cell carcinoma (3 papers); hepatocellular carcinoma (3); autism (2); Hyperglycemia (2); liver cancer (2); atherosclerosis (1); autoimmune disease (1); Cerebral ischemia (1); cerebrovascular diseases (1); colon cancer (1); diabetes (1); endothelial dysfunction (1); epilepsy (1); esophageal carcinoma (1); foot and mouth disease (1); infarction (1); inflammatory bowel disease (1); intellectual disabilities (1); lung squamous cell carcinoma (1); melanoma (1); pancreatic ductal adenocarcinoma (1); psoriasis (1); rheumatoid arthritis (1); sarcoma (1); squamous cell carcinoma (1); type 2 diabetes (1).